PYDC2 (pyrin domain containing 2)
Description:
May play a role in innate immunity by disrupting the interaction between PYCARD and NLRP3, thereby regulating the NLRP3 inflammasome. May also inhibit NF-kappa-B signaling distally by affecting the nuclear accumulation of RELA.
Synonyms: cPOP2; POP2
Tractability: No criterion of Open Targets' tractability assessment is met for any kind of drug.
Gene: Protein-coding gene on chromosome 3 (191,461,163 to 191,461,456, forward strand). Ensembl gene ENSG00000253548.
Subcellular location: Cytoplasm; Nucleus
Subcellular location (Human Protein Atlas): Nucleoli; Nucleoplasm; Cytosol
Gene Ontology:
Molecular function: protein binding
Biological process: negative regulation of inflammatory response; negative regulation of interleukin-1 beta production; negative regulation of NLRP3 inflammasome complex assembly; negative regulation of non-canonical NF-kappaB signal transduction; negative regulation of tumor necrosis factor-mediated signaling pathway; regulation of interleukin-1 beta production
Cellular component: cytoplasm; cytosol; nucleolus; nucleoplasm; nucleus
Genetic constraint (gnomAD): Loss-of-function variants: 1 observed, 0.7 expected, observed/expected ratio (o/e) 1.42, 90% interval 0.31 to 1.91. That is too few expected variants to judge how well the gene tolerates losing a copy. Missense variants: 123 observed, 116.29 expected, observed/expected ratio (o/e) 1.06, 90% interval 0.91 to 1.23. Synonymous variants: 51 observed, 47.15 expected, observed/expected ratio (o/e) 1.08, 90% interval 0.86 to 1.37.
Homologues: Orthologues: chimpanzee PYDC2 (100% identical), macaque PYDC2 (87% identical). Paralogues in human: NLRP2 (67% identical), NLRP7 (39% identical), NLRP14 (24% identical), NLRP11 (22% identical), NLRP5 (16% identical), NLRP8 (13% identical), NLRP13 (12% identical), NLRP1 (11% identical), NLRP12 (11% identical), NOD2 (9% identical), CIITA (7% identical), NOD1 (7% identical), and 8 more.
Diseases named in the same sentence as PYDC2 in open-access papers:
PYDC2 is named in the same sentence as 4 diseases in open-access papers, as found by Europe PMC text mining. Sharing a sentence is not in itself a finding about the gene and the disease. The quoted sentences say what the papers report.
endometriosis (1 paper, 2024). The growth of functional endometrial tissue in anatomic sites outside the uterine body. "We also evaluated the association of three polymorphisms in the NOD1, NOD2, and PYDC2 genes with the clinical manifestations of endometriosis." (PMID 40034240, 2024). "PYDC2 gene polymorphism analysis for endometriosis patients." (PMID 40034240, 2024). "PYDC2 rs293833 (c.242A>G) variant was detected in 12 endometriosis patients (22.2%)." (PMID 40034240, 2024). "However, the potential association between single nucleotide polymorphisms (SNPs) of the NOD1, NOD2, PYDC1, and PYDC2 genes and the predisposition to endometriosis risk remains unexplored." (PMID 40034240, 2024).
female infertility (1 paper, 2024). Diminished or absent ability of a female to achieve conception. "Our findings reveal that the NOD1 rs2075820 AA phenotype and PYDC2 rs293833 (c.242A > G) polymorphism are strongly associated with female infertility." (PMID 40034240, 2024).
Infertility (1 paper, 2024). "By investigating specific inflammasome-related polymorphisms, NOD1, and PYDC2 gene variants, we have uncovered potential associations with infertility and gastrointestinal complaints in affected individuals." (PMID 40034240, 2024). "Additionally, PYDC2-positive patients had significant differences in infertility and the presence of larger endometriomas." (PMID 40034240, 2024).
ovarian endometriosis (1 paper, 2024). A non-neoplastic disorder characterized by the growth of endometrial tissue in the ovaries. "Our findings suggest that NOD1 rs2075820 AA phenotype and PYDC2 rs293833 (c.242A>G) polymorphism is strongly associated with increased gastrointestinal complaints in ovarian endometriosis patients." (PMID 40034240, 2024). "In this study, we aim to investigate inflammasome regulators PYDC1 and PYDC2 and genetic variations in the NOD1 and NOD2 genes in patients with ovarian endometriosis." (PMID 40034240, 2024).